IRF3 (interferon regulatory factor 3)
Diseases named in the same sentence as IRF3 in open-access papers (continued):
Sharing a sentence is not in itself a finding about the gene and the disease.
infection (continued). "We examined IRF3 activation in A549 cells infected with either wt virus or a virus encoding a mutant ESEA PBM at six hours post-infection." (PMID 22911767, 2012). "The activity of the intact promoter upon infection was normal in IRF-1-deficient cells but strongly diminished in cells deficient in IRF-3 and -7, again consistent with an important role of IRF-3 in virus-induced up-regulation of Noxa." (PMID 21698224, 2011). "We employed a non-immortalized, non-transformed primary fibroblast cell line that is fully competent for IRF3 signaling and is susceptible and permissive to infection by HSV-1." (PMID 20454685, 2010). "Infection is exacerbated by the activity of IFN-I, shown convincingly by the increased resistance of IFNAR or IRF3-deficient mice to lethal infection." (PMID 19325882, 2009). "Symptomatic infection is also linked to several variations in the interferon regulatory factor 3 (IRF3) gene (a regulatory factor of interferon), and Myxovirus resistance 1 (Mx1) which encodes for an IFN-inducible guanosine triphosphate protease (GTPase) with antiviral gatekeeper properties." (PMID 40266979, 2025). "We designed A549 cell lines with stable knockdown of the IRF3 gene, in which even with the presence of Pte or Pin, the anti-EV-D68-effect was significantly impaired, suggesting that Pte or Pin mediates host innate immune activation associated with EV-D68 infection via the IRF3 signaling pathway." (PMID 36845118, 2023). "Therefore, examining the phosphorylation pattern and nuclear translocation post infection of key transcription factors IRF-3 and NF-κB revealed Omicron BA.1 and BA.2 variants to induce a delayed host immune response." (PMID 37001587, 2023). "Whether this K63-linked ubiquitination of IRF3 mediated by SHIP1 also occurs in other infections requires further investigations." (PMID 37366613, 2023). "Furthermore, infection of U937 cells with m6A-deficient HIV-1 generated from ALKBH5-overexpressed HEK293T cells induced approximately 2-fold higher phosphorylation of IRF3 and IRF7 when compared with control HIV-1." (PMID 33690734, 2021). "Infection of cells by RNA viruses is sensed through ligation of pattern recognition receptors linked to signalling pathways which activate nuclear factor κB (NFκB) and interferon regulatory factor-3 (IRF-3) to result in altered gene expression." (PMID 30423826, 2018). "In addition, IRF3/7-/- mice were more susceptible to infection with CHIKV via intranasal and oral routes, with IRF3/7-/- mice also able to transmit virus mouse-to-mouse without an arthropod vector." (PMID 26447467, 2015). "However, infection of mouse embryonic fibroblasts (MEFs) deficient for IRF3 with Newcastle disease virus induced a number of IRF3-independent direct response genes, including several p200 family proteins." (PMID 22363706, 2012). "Ubiquitination of TBK1 seemed an efficient tactic to activate IFN response because the endogenous TBK1 was K63-linked poly-ubiquitinated at 8 h post Sendai virus (SeV) infection and accompanied with phosphorylation of IRF3 and STAT1, the indications of the IFN production." (PMID 21364999, 2011). "However, pathogenic strains of WNV fail to stimulate the IRF-3 transcriptional activity until approximately 12–16 h post-infection, with maximal activation occurring much later." (PMID 21994652, 2010). "These pathways could certainly include a DNA sensor that acts via Irf3, as proposed for other infections, since Irf3 deficiency had a moderate effect on IFNβ expression in our experiments." (PMID 19578435, 2009). "Mice that lack IRF-3 were uniformly susceptible to severe infection with 100% lethality." (PMID 17676997, 2007). "Given the critical roles of TBK1 and IRF3 in RIG-I/MAVS-initiated IFN-inducing signaling pathway, we explored the role of SVCV-P-TBK1-IRF3 co-phase separated condensates during SVCV infection." (PMID 41363845, 2026).
infection (continued). "In parallel, neutralized conditioned media was used to pre-treat T84 IRF3-KO cells prior to VSV-Luc infection to evaluate functional antiviral protection." (PMID 41525418, 2026). "Despite NF‐κB‐ and IRF3‐mediated responses critical for antiviral immune responses to control infection, cellular infection and damage can lead to programmed cell death with bidirectional consequences depending upon the context." (PMID 39620586, 2025). "While not known to bind viral RNA directly, DDX50 binds TRIF and enhances phosphorylation and activity of both NF‐κB and IRF3 following poly(I:C) transfection or infection with dengue virus (DENV), SeV, HSV‐1, or vaccinia virus (VACV)." (PMID 39620586, 2025). "The irf3 expression displayed a modest increase at 7 days post-infection, peaking significantly at 21 days with an 8-fold increase over baseline (p < 0.01)." (PMID 40607404, 2025). "Previous evidence indicates that PEDV subverts IRF3 activation during infection, thereby blocking double-stranded RNA (dsRNA)-induced IFN-β production." (PMID 41156582, 2025). "We confirmed that Irf3/7−/− mice, infected with VLA1553 via the intraperitoneal route, developed readily detectable viraemia, with peak viraemia ~ 5.5–6.5 logs lower than those seen after infection of Irf3/7−/− mice with 4 log10CCID50 of CHIKV." (PMID 40355954, 2025). "Together, enhanced IRF3 activation at baseline and improved survival rates supported a model in which BCO2 deficiency establishes an infection-ready lung state." (PMID 41228402, 2025). "M3 efficiently inhibited the infection-induced activation of IRF3, which is caused by the phosphorylation of Ser386 in IRF3 by TBK1 in both early and later stages of infection." (PMID 39601535, 2025). "Upon infection, this configuration drives robust activation of type I interferon signaling via IRF3, upregulation of key interferon-stimulated genes (ISGs; Mx1, Rsad2), and concurrent suppression of virus-required metabolic pathways (P450, ACSF)." (PMID 41574307, 2025). "The results suggest that N-MYC and L-MYC are activated by infection in Irf3−/− mice and that rLon inhibits N-MYC and L-MYC deregulation in infected kidneys." (PMID 40000737, 2025). "The induction of viral RNA sensors (TLR3 and RIG-I), along with associated factors (IRF3, IFN-β, and OAS2), was low on the first day post-infection and reached peak expression by the third day." (PMID 41303574, 2025). "The expression levels of TBK1 and IRF3 were significantly increased in TRIM38 overexpressing cells after infection with ZIKV." (PMID 40006954, 2025). "To understand the CaMKII-dependent regulation of the expression of IFNα and β mRNA early in infection, we focused on IRF3 activation because the expression of IRF7 mRNA is regulated by IFN." (PMID 39601535, 2025). "The results showed a significant increase in the phosphorylation of STING, TBK1 and IRF3 upon PRV-ΔUS1 infection compared to PRV-WT." (PMID 41196926, 2025). "Next, QRTMs elegantly accessed the epigenetic states and functional features of viSEs assembly and validated H3K27ac, MED1, DNaseI, RNA pol II, CBP, IRF3, and p65 (co)-occupancies prior to and upon virus-infection." (PMID 40131776, 2025). "The activation of TBK1 and IRF3 is conventionally induced by the canonical RIG-I pathway later in infection." (PMID 39601535, 2025). "STING activation inhibits viral replication by coordinating interferon responses and modulating NF-κB/IRF3 signaling, and its inhibition exacerbates infection." (PMID 41459946, 2025). "Among these proteins, only US9 has been shown to impede the translocation of p-IRF3 during productive infection." (PMID 40872823, 2025). "Both Western blot and grayscale analysis showed that ARCN1 knockdown markedly increased IKKε protein abundance upon infection, accompanied by elevated phosphorylation of IRF3, STAT1, and STAT2." (PMID 41343552, 2025).
infection (continued). "This activation induces phosphorylation of interferon regulatory factor 3 (IRF3) at tyrosine residue 107 (Y107), promoting the activation of antiviral genes and triggering the immune response against infection." (PMID 40176892, 2025). "Consistently, phosphorylation of TBK1, MITA and IRF3 was markedly increased following infection with VACVOPG147/3A compared to wild-type VACV in THP-1 cells." (PMID 40498864, 2025). "The apoptotic role of IRF3 has been demonstrated during infections with several RNA viruses, such as paramyxovirus, vesicular stomatitis virus (VSV) and encephalomyocarditis virus (EMCV)." (PMID 38921776, 2024). "The activation of IRF3 was dependent on IAV-multiplicity of infection (MOI), and Zdhhc7−/− BMDMs had weaker response in both low and high MOI conditions." (PMID 39141356, 2024). "Using phosFlow, we confirmed a reduction in phospho-IRF3 levels in HOIP KO cells compared to WT but only observed active caspase-3 in 2% of cells during infection." (PMID 38001254, 2024). "In agreement with this, macrophages expressing short hairpin RNA (shRNA) against the virus uncoating factor D5 showed reduced IRF3 activation upon infection." (PMID 39431915, 2024). "We first analyzed the role of IRF3 in cell apoptosis during BPIV3 infection using HeLa cells expressing HA-IRF3." (PMID 39362857, 2024). "Meanwhile, upon SVCV infection, ubiquitination of endogenous irf3 was decreased in mylipb-null zebrafish (mylipb-/-) compared with WT zebrafish (mylipb+/+)." (PMID 38739631, 2024). "This leads to the downregulation of NF-κB and interferon regulatory factor 3 (IRF3), ultimately inhibiting interferon β (IFNβ) and interferon-inducible protein-10 (IP-10), which are genes involved in infection-triggered inflammation." (PMID 38542669, 2024). "When similar experiments were performed with VACV, an overall diminished activation of STING and IRF3 was observed upon infection of VACV.ΔB2 in line with previous data comparing VACV and ECTV." (PMID 39431915, 2024). "Deletion of Orf6 in BA.5 also increased the degree of infection-induced IRF3 and STAT1 phosphorylation and nuclear translocation." (PMID 38228858, 2024). "Phosphorylation of IRF3 level was increased from 9 h after infection and was lowered in HuR KO cells, whereas phosphorylation of p65 was slightly increased in both WT and HuR KO cells." (PMID 39348382, 2024). "HDAC3, HDAC4, HDAC5, and HDAC11 restrict infection of some viruses via regulation of IRF3, nuclear factor κB (NF-κB), or type I interferon (IFN) Janus kinase-signal transducers and activators of transcription (JAK-STAT) signaling pathways." (PMID 38461415, 2024). "As an indispensable transcription factor for antiviral innate immunity, IRF3 activity is tightly regulated by post-translational modifications to effectively protect the host from infection while avoiding excessive immunopathology." (PMID 38739631, 2024). "Consistent with their reduced innate immune triggering, we found Omicron BA.4 and BA.5 infection activated significantly less IRF3 phosphorylation than BA.2 infection." (PMID 38228858, 2024). "Zc3hav1 deficiency enhanced vesicular stomatitis virus (VSV, a ssRNA virus recognized by RIG-I) infection- or the dsRNA analog poly(I:C) transfection-induced Ifna4 mRNA expression and IRF3 phosphorylation." (PMID 39478149, 2024). "This demonstrates that Orf6 loss enhances IRF3 and STAT1 activation despite similar levels of infection in the first 24 h.p.i., confirming the important role of Orf6 in innate immune suppression and in distinguishing BA.5 from earlier Omicron subvariants." (PMID 38228858, 2024). "To further unveil the function of CPSF6 in virus-triggered innate immune responses, we measured the levels of phosphorylated IRF3 and TBK1 and observed that CPSF6 deficiency markedly facilitated TBK1 and IRF3 phosphorylation after VSV-eGFP infection." (PMID 38416782, 2024).
infection (continued). "Specifically, we observed an upregulation of antiviral genes, including rig-i, mx1, ifn-γ, irf3, and mda5, which are known to be crucial for effective antiviral responses in mucosal surfaces, particularly during the early stages of infection." (PMID 38218870, 2024). "Consistent with the activation of IFNB, we observed an increase in the levels of phosphorylated IRF3 with VPA treatment during infection with either live or UV-inactivated virus." (PMID 38932169, 2024). "Then, the phosphorylation of transcription factors IRF3 and p65 (RelA), a major component of NF-κB, was measured after the infection." (PMID 39348382, 2024). "The sequestration of IRF3 in IBs was further investigated at different hours post infection (hpi) of EBOV trVLPs." (PMID 38285487, 2024). "In fibroblasts, IRF3 activation was detectable at 10 h post-infection (hpi) and was abolished by the DNA replication inhibitor cytosine arabinoside (AraC), indicating that the sensing was mediated by replicated genomes." (PMID 39431915, 2024). "Upon SVCV infection, irf3 protein level and phosphorylation of irf3 were detected, which appeared to be higher in mylipb-null zebrafish (mylipb-/-) compared with WT zebrafish (mylipb+/+)." (PMID 38739631, 2024). "We also observed that ECTV.ΔvSlfn infection was sufficient to result in detectable activation of STING and IRF3, and this was abolished in cells deficient for cGAS or STING." (PMID 39431915, 2024). "FMT operates by altering the expression of IRF3 and enhancing the presence of butyrate-producing bacteria can alter the systemic immune response to infection." (PMID 39606629, 2024). "Type I IFN signaling was indeed activated upon EV71 infection, while EV71 suppressed IRF3 activation during sustained infection." (PMID 39058724, 2024). "Increased Orf6 levels suppressed host innate responses to infection by decreasing IRF3 and STAT1 signalling measured by transcription factor phosphorylation and nuclear translocation." (PMID 38228858, 2024). "The activity of IRF3 is strictly modulated by post-translational modifications (PTMs) to effectively protect the host from infection while avoiding excessive immunopathology." (PMID 38739631, 2024). "Knockdown of MORC3 can significantly enhance the expression levels of IRF3 upon SCRV infection while overexpressing MORC3 significantly inhibits the expression levels of IRF3 under SCRV infection." (PMID 38150467, 2023). "For OC43 infection, knockdown of IRF1 or IRF3 promoted viral protein synthesis compared to siRNA controls at both 2 and 3 days after infection." (PMID 37197656, 2023). "We demonstrated that M35 is necessary for the virus to successfully replicate in cell culture, as well as in the host organism, and that upon infection, tegument-delivered M35 immediately and directly counters induction of IRF3-dependent transcripts." (PMID 37289084, 2023). "Another group compared the response of mice deficient in IRF3, IRF7, or both IRF3 and IRF7 following infection with CHIKV." (PMID 37766276, 2023). "IFN-I needs to be tightly controlled to maintain host immune balance; thus, the post-translational modification of IRF3 plays a critical role in determining the immune state against infection." (PMID 37366613, 2023). "In vitro, our studies showed that the phosphorylation of TBK1 and IRF3 in RD cells increased at the early stage and then decreased later after EV-A71 infection, suggesting that the antiviral response was weakened." (PMID 36626364, 2023). "IFIT3 has been shown to promote viral clearance in epithelial models of infection through activation of IFN regulatory factor 3–mediated (IRF3-mediated) viral protein and RNA catabolism." (PMID 37071484, 2023). "To better understand the degradation processes of MAVS and IRF3, we analyzed the endogenous levels of these proteins in HT-29 cells infected with rSA11 and rSA11/WaVP3 viruses over the course of infection." (PMID 37905816, 2023).
infection (continued). "Elevated systemic levels of IFN-I were detected in the serum of WT and Irf3−/− mice 2 days post-infection, which declined by day 4 post-infection." (PMID 37737190, 2023). "Next, we conducted immunoblotting assays and found that PTK2B knockdown reduced the levels of phosphorylated STING, TBK1 and IRF3 induced by infection with HSV1-GFP." (PMID 37989995, 2023). "For instance, rapid IRF3-dependent KC death is seen in mice following infection with human adenovirus." (PMID 37691953, 2023). "229E viral protein synthesis was increased in cells treated with siRNA oligos against IRF3 or IRF7 compared to siRNA controls at 2 days after infection." (PMID 37197656, 2023). "IRF3 activation effectively promotes transcription of antiviral genes during OC43 or 229E infection." (PMID 37197656, 2023). "The levels further increase in all brain parts of Irf7−/− animals 7 days post-infection compared to WT and Irf3−/− mice." (PMID 37737190, 2023). "The phosphorylation modifications of TBK1 and IRF-3 play important roles in the cellular response to infection, inflammation, and other stressful stimuli." (PMID 37515271, 2023). "Consistently, the levels of phosphorylated TBK1 and IRF3 induced by VSVΔM51-GFP infection were decreased in PTK2B-knockdown THP1 cells compared with those in the control cells." (PMID 37989995, 2023). "Consistently, PTK2B overexpression not only augmented the levels of phosphorylated STING, TBK1 and IRF3 induced by HSV1-GFP infection but also increased the levels of phosphorylated TBK1 and IRF3 induced by VSVΔM51-GFP infection." (PMID 37989995, 2023). "This was the case in our study where the expression of IRF3 was decreased during infection of 229E or OC43." (PMID 37197656, 2023). "A significantly elevated amount of viral RNA was found in serum of Irf7−/− mice 2 days post-infection when compared to WT and Irf3−/− mice." (PMID 37737190, 2023). "In the presence of VitD and rxrbb during GCRV infection, the double knockout of grass carp vdra and vdrb significantly induced the transcriptions of mda5, rig-I, mavs, tbk1, irf3, irf7, and mx1." (PMID 37466438, 2023). "Highly activated TFs include STAT1, STAT2, and IRF3, which are responsible for innate and acquired immune responses and host defenses against infection." (PMID 38042877, 2023). "As in normal cells, both transcription factors IRF3 and NFκB become activated and translocate into the nucleus of transformed cells upon H1-PV or MVMp infection." (PMID 37111493, 2023). "Our results also indicated that the IRF3 agonist almost restrained the expressions of cytokines and almost reversed the effect of EV-A71 infection on cytokines production." (PMID 36626364, 2023). "Upon infection, orf6 blocks the activation of interferon regulatory factor 3 (IRF3) through a short peptide sequence in its C-terminal tail." (PMID 37790934, 2023). "We aimed to elicit robust antitumor immunity by preventing viral inactivation of the cGAS/STING/IRF3 pathway after infection of cancer cells." (PMID 37016144, 2023). "Interferon Regulatory Factor (IRF3) is a transcriptional regulator of type I IFN, involved in response to pathogenic infection in the innate immune system." (PMID 37761018, 2023). "The protein levels of NF-κB/RelA and IRF3 are stable within 24 h infection, while the level of IRF7 is increased at 12 h p.i." (PMID 37423306, 2023). "Consistently, we found that Ptk2b knockout decreased the levels of phosphorylated TBK1 and IRF3 induced by HSV1-GFP or VSVΔM51-GFP infection." (PMID 37989995, 2023). "During infection with SeV and VSV, the deficiency of STING blocks the activation of IRF3 and the expression of ISG and IFN-β." (PMID 38005886, 2023). "Consistently, Ptk2b deficiency reduced the levels of phosphorylated STING, TBK1 and IRF3 stimulated by HSV1-GFP infection." (PMID 37989995, 2023).